ETFDH (electron transfer flavoprotein dehydrogenase)
Description:
Links fatty acid beta-oxidation and amino acid catabolism to the respiratory chain by transferring electrons from the electron transfer flavoprotein (ETF) to ubiquinone.
Synonyms: ETFQO; MADD
Tractability: PROTAC: ubiquitination databases record sites on it; its protein half-life has been measured.
Gene: Protein-coding gene on chromosome 4 (158,671,968 to 158,710,758, forward strand). Ensembl gene ENSG00000171503.
Subcellular location: Mitochondrion inner membrane
Subcellular location (Human Protein Atlas): Mitochondria; Cytosol; Nucleoplasm
Pathways (Reactome):
Metabolism: Respiratory electron transport
Gene Ontology:
Molecular function: 4 iron, 4 sulfur cluster binding; electron transfer activity; electron-transferring-flavoprotein dehydrogenase activity; oxidoreductase activity; protein binding; quinone binding; ubiquinone binding; flavin adenine dinucleotide binding; iron-sulfur cluster binding
Biological process: electron transport chain; fatty acid beta-oxidation using acyl-CoA dehydrogenase; respiratory electron transport chain; response to oxidative stress
Cellular component: mitochondrial inner membrane; mitochondrial membrane; mitochondrion
Genetic constraint (gnomAD): Loss-of-function variants: 19 observed, 24.75 expected, observed/expected ratio (o/e) 0.77, 90% interval 0.53 to 1.13. The upper end of that interval is the gene's LOEUF score, 1.13, which puts it in group 4 of 6, group 1 being the genes least tolerant of losing a copy. Missense variants: 316 observed, 341.37 expected, observed/expected ratio (o/e) 0.93, 90% interval 0.84 to 1.02. Synonymous variants: 113 observed, 120.57 expected, observed/expected ratio (o/e) 0.94, 90% interval 0.8 to 1.1.
Gene-disease validity (ClinGen):
ClinGen rates the evidence that ETFDH causes each of these diseases.
multiple acyl-CoA dehydrogenase deficiency (autosomal recessive): Definitive.
Homologues: Orthologues: macaque ETFDH (99% identical), chimpanzee ETFDH (95% identical), pig ETFDH (95% identical), dog ETFDH (95% identical), rabbit ETFDH (94% identical), mouse Etfdh (92% identical), guinea pig ETFDH (91% identical), rat Etfdh (86% identical), tropical clawed frog etfdh (83% identical), zebrafish etfdh (80% identical), Drosophila melanogaster Etf-QO (65% identical), Caenorhabditis elegans let-721 (60% identical).
Diseases named in the same sentence as ETFDH in open-access papers:
ETFDH is named in the same sentence as 68 diseases in open-access papers, as found by Europe PMC text mining. Sharing a sentence is not in itself a finding about the gene and the disease. The quoted sentences say what the papers report.
multiple acyl-CoA dehydrogenase deficiency (53 papers, 2009 to 2025). "The LSM patients were mainly multiple acyl-CoA dehydrogenase deficiency (MADD) caused by the ETFDH gene mutation." (PMID 36326420, 2022). "Variations in the electron transfer flavoprotein dehydrogenase (ETFDH) gene cause multiple acyl-CoA dehydrogenase deficiency (MADD), and have a manifestation of LSM." (PMID 36588907, 2022). "Studies found that the riboflavin (vitamin B2) responsive multiple acyl-CoA dehydrogenase deficiencies (RR-MADD) caused by ETFDH mutation and the clinical symptoms of patients treated with riboflavin can be significantly improved." (PMID 36326420, 2022). "The variants of electron transfer flavoprotein (ETFA, ETFB) and ETF dehydrogenase (ETFDH) are the leading cause of glutaric aciduria type II (GA-II)." (PMID 34573316, 2021). "Classical multiple acyl-CoA dehydrogenase deficiency (MADD) is known to occur secondary to mutations in electron transfer flavoprotein dehydrogenase (ETFDH) gene." (PMID 29615056, 2018). "Multiple acyl-CoA dehydrogenase deficiency (MADD) is an autosomal recessive disorder caused by deficiency of electron transfer flavoprotein or electron transfer flavoprotein dehydrogenase." (PMID 25200064, 2014). "Conversely, in NB-12, two compound heterozygous variants c.1823G > A (p.G608D, non-conservative amino acid change) and c.770A > G (p.Y257C, non-conservative amino acid change) of uncertain significance were detected in the ETFDH gene associated with glutaric aciduria type II." (PMID 30612563, 2019). "Late-onset multiple acyl-CoA dehydrogenase deficiency (MADD) is an autosomal recessive disease chiefly caused by mutations in ETFDH gene." (PMID 40533849, 2025). "A prime example is multiple acyl-CoA dehydrogenase deficiency (MADD), caused by mutations in ETFDH, ETFA, or ETFB genes encoding electron transfer flavoprotein or its dehydrogenase." (PMID 40963932, 2025). "Multiple acyl-CoA dehydrogenase deficiency (MADD) is a rare autosomal recessive metabolic disorder primarily caused by defects in electron transfer flavoprotein (ETF) or ETF dehydrogenase (ETFDH)." (PMID 40673202, 2025). "Multiple acyl-CoA dehydrogenase deficiency (MADD) also known as glutaric academia type II or lipid-storage myopathy—is caused by loss-of-function variants in ETFDH, ETFA, ETFB or, more rarely, FLAD1." (PMID 40963932, 2025). "In humans, ETF and ETFdh variants are typical causes of multiple acyl-CoA dehydrogenase deficiency (MADD) and glutaric aciduria type II." (PMID 39456717, 2024). "This article reports the characterization of two siblings diagnosed with late-onset multiple Acyl-CoA dehydrogenase deficiency (MADD) caused by mutations in electron transfer flavoprotein(ETF)-ubiquinone oxidoreductase (ETF-QO) (ETFDH) gene." (PMID 36683804, 2023). "Mutations in ETFDH, coding for the protein electron-transferring flavoprotein dehydrogenase, result in multiple acyl-CoA dehydrogenase deficiency (MADD), also known as glutaric aciduria types IIA-C." (PMID 37508007, 2023). "The electron-transfer flavoprotein dehydrogenase gene (ETFDH) that encodes the ETF-ubiquinone oxidoreductase (ETF-QO) has been reported to be the major cause of multiple acyl-CoA dehydrogenase deficiency (MADD)." (PMID 30709034, 2019). "Deficiency of electron transfer flavoprotein dehydrogenase (ETFDH) is associated with multiple acyl-CoA dehydrogenase deficiency (MADD)." (PMID 30424791, 2018). "Glutaric acidemia type II (GAII), also known as multiple acyl-CoA dehydrogenase deficiency, results from defects in the electron transfer flavoprotein (ETF) or ETF dehydrogenase (ETFDH)." (PMID 39963347, 2025). "Multiple acyl-CoA dehydrogenase deficiency (MADD) is an autosomal recessive disorder resulting from pathogenic variants in three distinct genes, with most of the variants occurring in the electron transfer flavoprotein-ubiquinone oxidoreductase gene (ETFDH)." (PMID 38221620, 2024).
multiple acyl-CoA dehydrogenase deficiency (continued). "The ETF/ETFDH complex transfers electrons from the dehydrogenases to the electron transport chain, and the deficiency leads to multiple acyl-CoA dehydrogenase deficiency (MADD)." (PMID 40225143, 2023). "These are the associations MCCC2—hydroxyvalerylcarnitine (3-methylcrotonylglycinuria), ETFDH—hexanoylcarnitine (glutaric acidemia type II) and SARDH—sarcosine (sarcosinemia)." (PMID 35888728, 2022). "Multiple acyl-CoA dehydrogenase deficiency (MADD) is a rare autosomal recessive disorder that may be associated with a mutation found in the gene encoding electron transfer flavoprotein (ETF) or in the gene encoding electron transfer flavoprotein dehydrogenase (ETFDH)." (PMID 34827632, 2021). "The electron-transfer flavoprotein dehydrogenase gene (ETFDH) encodes the ETF-ubiquinone oxidoreductase (ETF-QO) and has been reported to be the major cause of multiple acyl-CoA dehydrogenase deficiency (MADD)." (PMID 34064479, 2021). "A zebrafish knockout mutant for the electron transfer flavoprotein dehydrogenase (etfdh), termed “xavier”, closely mimics the characteristics observed in glutaric aciduria type II." (PMID 32971894, 2020). "We report a Southern Min Chinese family with two siblings carrying the c.250G > A (p.Ala84Thr) mutation in the ETFDH gene who presented with typical features of adolescent-onset riboflavin responsive multiple acyl-CoA dehydrogenase deficiency (MADD) associated lipid-storage myopathy." (PMID 31852447, 2019). "In multiple acyl-CoA dehydrogenase deficiency (MADD), mutations in ETFa, ETFb, or ETFDH, lead to decreased ATP production with an accumulation of organic acids, including glutaric acid as well as acyl-carnitines." (PMID 32038305, 2019). "Mutations of ETFDH cause the onset of Multiple acyl-CoA dehydrogenase deficiency (MADD)." (PMID 30424791, 2018). "Glutaric acidemia type-II, caused by mutations of either ETFA, ETFB or ETFDH that collectively encode the OXPHOS enzyme electron transfer flavoprotein, is also characterized by PKD." (PMID 28205547, 2017). "Multiple acyl-CoA dehydrogenase deficiency (MADD), also known as glutaric aciduria type II, is an autosomal-recessive inherited disorder caused by mutations in electron transfer flavoprotein (ETF) or electron transfer flavoprotein dehydrogenase (ETFDH)." (PMID 20020044, 2009). "The multiple acyl-CoA dehydrogenase deficiency (MADD), also called GAII, is caused by genetic defects in the electron transfer flavoprotein ETF and its dehydrogenase ETFDH, which are encoded by ETFA, ETFB, and ETFDH, respectively." (PMID 40225143, 2023). "Multiple acyl-CoA dehydrogenase deficiency (MADD) is a riboflavin-responsive lipid-storage myopathy caused by mutations in the EFTA, EFTB or ETFDH genes." (PMID 31852447, 2019). "Multiple Acyl-CoA Dehydrogenase Deficiency (MADD), also known as Glutaric Acidemia type II (GAII), is an autosomal recessive disorder caused by pathogenic variants in the genes encoding the electron transfer flavoprotein (ETF) or its dehydrogenase (ETFDH)." (PMID 41462609, 2025). "Multiple acyl-CoA dehydrogenase deficiency (MADD) is a fatty acid and amino acid oxidation defect caused by a deficiency of the electron-transfer flavoprotein (ETF) or the electron-transfer flavoprotein dehydrogenase (ETFDH)." (PMID 34440319, 2021).
lipid storage myopathy (6 papers, 2018 to 2025). "Histopathology confirmed lipid storage myopathy, and exome sequencing (ES) identified electron transfer flavoprotein dehydrogenase gene (ETFDH) mutations." (PMID 41121198, 2025). "Late-onset MADD is the most common lipid storage myopathy, predominantly caused by defects in electron transfer flavoprotein dehydrogenase (ETFDH)." (PMID 38365830, 2024). "A repeat biopsy in one sibling subsequently showed features of lipid storage myopathy and genetic analysis identified a homozygous mutation (c.250G > A) in the ETFDH gene in both siblings and carriage of the same mutation by both parents." (PMID 31852447, 2019). "Mutations in ETFDH should be screened for in individuals with lipid-storage myopathy to identify patients who are responsive to riboflavin." (PMID 31852447, 2019). "ETFDH c.770A > G (Tyr257Cys) was not reported in 1000 Genome or ExAC databases but has been reported with ETFDH c.250G > A in riboflavin-responsive lipid storage myopathy." (PMID 29615056, 2018). "These cases emphasize the importance of considering the diagnosis of a lipid storage myopathy and RR-MADD in patients presenting with muscle weakness, myalgia and exercise intolerance, and of screening for mutations in the ETFDH gene to identify patients who are responsive to riboflavin therapy." (PMID 31852447, 2019).
glutaric acidemia (4 papers, 2018 to 2024). "In addition, mutations in ACADS gene were detected in four cases of short-chain acyl-CoA dehydrogenase deficiency, and two of them were accompanied with glutaric acidemia (type I or type II ) carried mutations in the GCDH and ETFDH genes, respectively." (PMID 29731766, 2018).
Encephalopathy (3 papers, 2009 to 2023). Encephalopathy is a term that means brain disease, damage, or malfunction. "Results indicate that GA-II with or without recurrent vomiting, encephalopathy, metabolic acidosis, and hypoglycemia is linked significantly with likely pathogenic variants such as ETFDH:p.Gln269His, ETFDH:p.Ser442Leu, ETFDH:p.Gly472Arg, and ETF:p.Ile346Phefs*19." (PMID 34573316, 2021). "The metabolic decompensation may be life-threatening with encephalopathy and hyperammonemia, and neither clinical symptoms nor biochemical findings allow distinguishing RFVT1 deficiency from MADD deficiency (caused by biallelic ETFA, ETFB and ETFDH variants)." (PMID 37510312, 2023).
coenzyme Q10 deficiency (2 papers, 2019 to 2023). A genetically heterogeneous condition, typically inherited in an autosomal recessive fashion, characterized by coenzyme Q10 deficiency. "In isolated forms of coenzyme Q10 deficiency (caused by mutations in gene for electron transfer flavoprotein dehydrogenase, ETFDH), CK elevation is also present." (PMID 38254650, 2023). "It is also important to note that riboflavin supplementation attenuates ETFDH mutation-induced secondary coenzyme Q10 deficiency." (PMID 30709034, 2019).
deficiencies (2 papers, 2019 to 2025). "ETFDH has been associated with multiple acyl-CoA dehydrogenase deficiencies and mitochondrial disorders." (PMID 40634996, 2025). "This demonstration of the genetic basis for MADD provides molecular insight into mitochondrial dysfunctions induced by ETFDH deficiency." (PMID 30709034, 2019). "It has been shown that late-onset MADD patients with ETFDH mutations frequently have secondary coenzyme Q10 deficiencies." (PMID 30709034, 2019).
hepatic cancer (2 papers, 2023 to 2025). "Notably, G6PD, FASN and LPIN1 are upregulated in HCC compared with non-tumor livers in both HCC cohorts while ETFDH is downregulated, highlighting the likely role of lipid metabolism and PPP pathways in liver cancer." (PMID 37301960, 2023).
metabolic myopathies (2 papers, 2018 to 2025). "Genetic investigations, performed via NGS targeting a large panel of genes associated with metabolic myopathies, detected ETFDH gene mutations in all patients." (PMID 41462609, 2025). "The affected individuals show a severe metabolic myopathy, resembling what is seen in individuals with Electron Transfer Flavoprotein Dehydrogenase (ETFDH) defects." (PMID 29316637, 2018).
Obesity (2 papers, 2016 to 2020). Accumulation of substantial excess body fat. "Among these candidates, butyrylcholinesterase (Bche) and Sucrase-isomaltase (Si) peptidylprolyl isomerase D (PpiD) and electron-transferring-flavoprotein dehydrogenase (EtfdH) are all well-known for body weight or obesity." (PMID 27203862, 2016).
a nephropathy (1 paper, 2025). "The intermediary effect of ETFDH inhibitors on immunoglobulin a nephropathy (IgAN) via plasma proteins." (PMID 40898824, 2025).
acute lymphoblastic leukemia (1 paper, 2026). Leukemia with an acute onset, characterized by the presence of lymphoblasts in the bone marrow and the peripheral blood. "In contrast to muscle, ETFDH is a non-essential gene in acute lymphoblastic leukemia NALM6 cells, and its expression is reduced across human cancers." (PMID 42085321, 2026).
Alzheimer disease (1 paper, 2024). A progressive, neurodegenerative disease characterized by loss of function and death of nerve cells in several areas of the brain leading to loss of cognitive function such as memory and language. "Previous studies have shown that ETFDH is a potential target for ageing and Alzheimer’s disease." (PMID 38167102, 2024).
anal carcinoma (1 paper, 2024). "In SMR analyses, ABCC8/KCNJ11, DPP4, PPARG, ETFDH, and PRKAB1 were associated with anal carcinoma, cardia cancer, and pancreatic cancer." (PMID 38504335, 2024).
bladder cancer (1 paper, 2021). "Moreover, increasing the expressions of NCF2, ETFDH, and SON genes are positively correlated with the incidence of death from bladder cancer." (PMID 34589136, 2021).
breast carcinoma (1 paper, 2022). "For example, the mRNA signatures ETFDH, EGF, PRKAB1, ALOX5, DHRS9, MTHFR, and MGHH are in the maximum interaction network and are connected to other breast-cancer-related, frequently altered genes." (PMID 36551179, 2022).
Charcot-Marie-Tooth disease (1 paper, 2025). An inherited degenerative disorder involving the peripheral nerves. "According to OMIM, SURF1 and ETFDH are associated with Charcot-Marie-Tooth disease (MIM #616684) and glutaric acidemia IIC (MIM #231680), respectively, with an autosomal recessive inheritance pattern." (PMID 40634996, 2025).
epilepsy (1 paper, 2024). A brain disorder characterized by episodes of abnormally increased neuronal discharge resulting in transient episodes of sensory or motor neurological dysfunction, or psychic dysfunction. "This MR study suggests that the antihyperglycemic drug target gene ETFDH may increase the risk of epilepsy and that metformin is an inhibitor of the ETFDH gene." (PMID 38167102, 2024). "The preliminary study of DrugBank data and the results in this paper indicate that ETFDH, the target of metformin, is associated with an elevated risk of epilepsy and that metformin has a potential therapeutic value for epilepsy, although the specific mechanism still needs to be further explored." (PMID 38167102, 2024). "The study identified three anti-glucose drug target genes, ETFDH, CYP21A2 and CYP2D6, associated with epilepsy." (PMID 38167102, 2024). "A search of DrugBank revealed that metformin, an anti-glucose drug, is an inhibitor of the ETFDH gene and may have a potential therapeutic effect on epilepsy." (PMID 38167102, 2024). "Furthermore, as an inhibitor of the ETFDH gene, metformin has the potential to be used as a therapeutic treatment for epilepsy." (PMID 38167102, 2024). "Meanwhile, the results of this study reveal that ETFDH is a potential target for anti-epilepsy." (PMID 38167102, 2024). "It was discovered that three antidiabetic drug target genes, ETFDH, CYP21A2 and CYP2D6, were involved in the occurrence of epilepsy." (PMID 38167102, 2024).
Hepatic steatosis (1 paper, 2022). Steatosis is a term used to denote lipid accumulation within hepatocytes. "In addition, mice carrying a knock-in ETFDH mutation displayed diet-dependent phenotypes, including hepatic steatosis and elevated levels of acyl-carnitine species." (PMID 36154948, 2022).
Hypoglycemia (1 paper, 2021). A decreased concentration of glucose in the blood. "In one patient with persistent metabolic acidosis, hypoglycemia, and a high anion gap, the ETFDH:p.Gly472Arg, and ETFB:p.Pro94Thrfs*8 variants were identified in a homozygous, and heterozygous state, respectively." (PMID 34573316, 2021). "In this study, six variants were found in two genes (ETFDH and ETFB) associated with GA-II, recurrent vomiting, and hypoglycemia." (PMID 34573316, 2021).
meningitis (1 paper, 2020). A disorder characterized by acute inflammation of the meninges of the brain and/or spinal cord. "We reported a case of GA II with purulent meningitis and septicemia and identified a novel ETFDH gene mutation in a female infant." (PMID 32393189, 2020).
Onset (1 paper, 2020). The age group in which disease manifestations appear. "Several adult-onset GA II cases have been reported with ETFDH mutations, almost 190 different variations of this gene have been identified, but few ETFDH mutations have been described in neonatal-onset GA II patients." (PMID 32393189, 2020).
organic acidemias (1 paper, 2021). "With the suspicion of organic acidemias early in her life, the coding regions and splicing sites of GCDH, ETFA, ETFB, ETFDH, IVD were evaluated by PCR and sequencing and no pathogenic variant was identified." (PMID 35083005, 2021).
pancreatic cancer (1 paper, 2024). "Moreover, ABCC8 (OR = 1.142; 95% CI: 1.013–1.287; P-value = 0.030), ETFDH (OR = 1.249; 95% CI: 1.006–1.550; P-value = 0.044), and PRKAB1 (OR = 0.798; 95% CI: 0.662–0.962; P-value = 0.018) were associated with pancreatic cancer risks." (PMID 38504335, 2024).